STIM1 (stromal interaction molecule 1)
Diseases named in the same sentence as STIM1 in open-access papers (continued):
Sharing a sentence is not in itself a finding about the gene and the disease.
cardiac hypertrophy (22 papers, 2014 to 2024). "When STIM1 extinction occurs 3 weeks after the establishment of pressure overload-induced cardiac hypertrophy, mice also exhibit marked ventricular dilatation associated with systolic dysfunction compared to WT mice, reflecting a more rapid transition to HF." (PMID 36291148, 2022). "Several studies proposed a pathological key role for STIM1/Orai1-mediated SOCE in altered Ca2+ signaling underlying the development of cardiac hypertrophy by changing the fetal gene program regulated by NFAT signaling." (PMID 29618985, 2018). "Increased STIM1 function has also been associated with cardiac hypertrophy and hypertension, characterized by enhanced spontaneous Ca2+ transients and downstream transcription coupling, and decrease in its function has been proposed to ameliorate these cardiac disorders." (PMID 32330125, 2020). "Likewise, increased TRPC5 expression in human heart failure and STIM1 elevation are linked to cardiac hypertrophy." (PMID 31878108, 2019). "Therefore, enhanced AMPK activation caused by increased STIM1 expression could activate more PFK-1 to elevate glycolysis in cardiac hypertrophy (Figure 4➃), while the case is another way around in diabetic cardiomyopathy." (PMID 37685995, 2023). "In this review, we first discussed STIM1-dependent signaling in cardiomyocytes and metabolic changes in cardiac hypertrophy and diabetic cardiomyopathy." (PMID 37685995, 2023). "In cardiomyocytes, it is suggested that STIM1 contributes to the development of cardiac hypertrophy and advancement of heart disease, although how STIM1 expression and functionality impact S/ER Zn2+ and Zn2+ transporters has not yet been investigated." (PMID 37326614, 2023). "The increased expression of STIM1 has been reported in cardiac hypertrophy, while the decreased expression of STIM1 has been shown in diabetic cardiomyopathy." (PMID 37685995, 2023). "STIM1 would, therefore, be a key element in the development and the persistence of compensated cardiac hypertrophy to preserve the transition to HF." (PMID 36291148, 2022). "The data suggested that inhibition of store-operated Ca2+ entry can reduce myocardial hypertrophy induced by phenylephrine, which indicates that the STIM1-Orai1-Ca2+ dependent pathway is located upstream of hypertrophy." (PMID 35303866, 2022). "Since the establishment of a role for STIM1/Orai1 in cardiac hypertrophy, several additional studies have tried to examine the mechanisms driving the increase in STIM1 during hypertrophy." (PMID 35821821, 2022). "TRPCs and Orai1 are upregulated, and STIM1 is activated, during the progression of cardiac hypertrophy." (PMID 34564947, 2021). "Recently, it has been shown that up‐regulated STIM1‐governed SOCE plays a critical role in cardiac hypertrophy and arrhythmogenesis." (PMID 33755308, 2021). "It is also of interest that another ER-resident protein, SOCE-associated regulatory factor (SARAF), when overexpressed, can mitigate the effect of STIM1 in cardiac hypertrophy and diastolic dysfunction." (PMID 32330125, 2020). "For example, induction of cardiac hypertrophy by pressure overload results in upregulation of STIM1 and Orai1 expression in mouse cardiac tissue, and cardiomyocyte-specific suppression of STIM1 and Orai1 attenuates the hypertrophic response." (PMID 32086252, 2020). "In accordance, STIM1 knock-down was shown to prevent cardiac hypertrophy in adult rats subjected to aortic banding." (PMID 31498847, 2019). "Stromal interaction molecule 1 (STIM1), an endo/sarcoplasmic reticulum Ca2+ sensor, has been shown to control a Ca2+-dependent signal that promotes cardiac hypertrophy." (PMID 29145451, 2017). "Taken together, these data indicate that gastrodin acts to suppress the expression of STIM1 and Orai1 proteins in both in vivo and in vitro models of cardiac hypertrophy." (PMID 28487655, 2017).
cardiac hypertrophy (continued). "(c) Suppression of SOCE by an Orai1 inhibitor RO2959, Orai1-siRNAs, or STIM1-siRNAs all attenuated the phenylephrine-induced hypertrophy, demonstrating a critical role of SOCE, STIM1 and Orai1 in promoting cardiac hypertrophy." (PMID 28487655, 2017). "In our study, pyridostigmine inhibited the expression of CaN, NFAT3, p‐GATA4 and STIM1, prevented Orai1/STIM1 complex formation and attenuated cardiac hypertrophy." (PMID 28296184, 2017). "Postmortem analysis of ventricular weight normalized for body weight were calculated to measure the extent of cardiac hypertrophy, STIM1 mutant mice displayed a ≈35% lower ratio than the control group." (PMID 27150728, 2016). "The precise role of STIM1 and the attendant Ca2+ signaling relevant to cardiac hypertrophy and ventricular function has largely been overlooked." (PMID 27150728, 2016). "Together, these data suggest that STIM1-mediated cardiac hypertrophy in response to TAC occurs through activation of FAK-Akt and ERK1/2 signaling pathways." (PMID 27150728, 2016). "A growing body of literature suggests that STIM1 plays a key role in the development of pathological cardiac hypertrophy." (PMID 27150728, 2016). "Accumulating evidence suggests that STIM1 is involved in various pathophysiological processes such as inflammatory immune response, cardiac hypertrophy and hypertension." (PMID 24736434, 2014). "However, upon the discovery of STIM1 and Orai1 as key regulators of SOCE and with STIM1/Orai1-mediated SOCE being associated with cardiac hypertrophy, there was a growing appreciation of this signaling mechanism in the heart." (PMID 35821821, 2022). "Similarly, pharmacological induction of cardiac hypertrophy by phenylephrine and endothelin-1 is attenuated by suppression of STIM1 or Orai1 in rodent cardiomyocytes." (PMID 32086252, 2020). "Moreover, trans-aortic banding in mice, which also results in cardiac hypertrophy, was shown to increase STIM1-expression and SOCE." (PMID 31498847, 2019). "In addition to STIM1 role in cardiac homeostasis, compelling evidences characterized the role of STIM1-mediated SOCE in cardiac hypertrophy." (PMID 29618985, 2018). "STIM1+/–mice had significantly less cardiac hypertrophy than WT TAC mice." (PMID 29145451, 2017). "Likewise, two other groups reported that STIM1 knockdown induced loss of SOCE and suppressed agonist-triggered cardiac hypertrophy in primary cultured neonatal cardiomyocytes." (PMID 29145451, 2017). "Although our present results implicate that gastrodin may act through STIM1-Orai1 expression to inhibit cardiac hypertrophy, we cannot exclude the possibility that gastrodin could also act on other hypertrophy-related pathways/factors such as TRPC channels." (PMID 28487655, 2017). "One possible explanation is that STIM1-deficient patients have early mortality without clinically important cardiac hypertrophy that developed over an extended period of time." (PMID 29145451, 2017). "Indeed, tamoxifen-induced STIM1 knockout mice were protected against pressure overload-induced cardiac hypertrophy." (PMID 27150728, 2016). "Finally, we report that acute STIM1 genetic deletion attenuate pressure overload-induced cardiac hypertrophy by preventing focal adhesion activation and its downstream signaling." (PMID 27150728, 2016). "Therefore, increased STIM1 expression in cardiac hypertrophy could enhance glucose uptake through upregulating GLUT4 (Figure 4➀)." (PMID 37685995, 2023). "In terms of how STIM1 is associated with FA oxidation, our speculation is that STIM1 could decrease carnitine-palmitoyl transferase 1 (CPT1) expression or activity, leading to the reduction in FA oxidation in cardiac hypertrophy (Figure 5➂)." (PMID 37685995, 2023). "Therefore, this study examined changes in vagal discharge and investigated whether pyridostigmine can inhibit CaN/NFAT3/GATA4 and suppress Orai1/STIM1 complex formation as well as improve cardiac function in pressure overload‐induced cardiac hypertrophy." (PMID 28296184, 2017).
cardiac hypertrophy (continued). "Although modifying the expression of STIM1 may be a promising therapeutic approach for cardiac hypertrophy and heart failure, identifying the point of transition from an adaptive state to a decompensated response and making a timely inhibition of STIM1 might also be of great importance." (PMID 29145451, 2017). "The release of H+ from these residues activates STIM1, thereby enhancing STIM1-mediated SOCE and promoting cardiac hypertrophy." (PMID 39454952, 2024). "Molecular mechanisms linking the HBP to cardiac hypertrophy through GFAT overexpression, high Glc, phenylephrine, NOX4, and STIM1 models." (PMID 36353238, 2022). "Together, these results showed that gastrodin inhibited cardiac hypertrophy and it also reduced the SOCE via its action on the expression of STIM1 and Orai1." (PMID 28487655, 2017). "We demonstrated that gastrodin attenuated the cardiac hypertrophy and suppressed the SOCE via its action on Orai1 and STIM1 expression." (PMID 28487655, 2017). "Taken together, this study demonstrated that gastrodin attenuated the cardiac hypertrophy and suppressed the SOCE via its action on Orai1 and STIM1 expression." (PMID 28487655, 2017). "Moreover, intracellular alkalization induced by agents such as Angiotensin II or NH4Cl enhances STIM1-mediated SOCE, promoting cardiac hypertrophy." (PMID 39454952, 2024). "Stromal interaction molecule 1 (STIM1), a well-established calcium (Ca2+) sensor of endoplasmic reticulum (ER) Ca2+ store, is increasingly recognized as a critical player in mediating both cardiac hypertrophy and diabetic cardiomyopathy." (PMID 37685995, 2023). "Understanding the mechanism of STIM1, Orai1 and TRPC1 may prevent cardiac hypertrophy or heart failure." (PMID 35303866, 2022). "Since STIM1, Orai1, and TRPCs are central mediators of SOCE, directly interfering with their expressions through the corresponding knockdowns and knockouts can help to elucidate the specific role of SOCE during the progression of cardiac hypertrophy." (PMID 34564947, 2021). "The hearts of WT TAC mice had remarkable cardiac hypertrophy, while hearts from STIM1+/–TAC mice showed no marked changes." (PMID 29145451, 2017). "The development of novel pharmacological therapeutics that can prevent Oria1/STIM1 puncta formation and inhibit the CaN/NFAT3 pathway may afford better protection against cardiac hypertrophy and heart failure." (PMID 28296184, 2017). "In the present study, pyridostigmine may have suppressed the formation of Orai1/STIM1 complex, resulting in inhibition of the activation of the CaN/NFAT3/GATA4 signalling pathway and attenuation of cardiac hypertrophy." (PMID 28296184, 2017). "With regard to the various in vivo experimental models of cardiac hypertrophy, there are differences as to whether or not STIM1 expression is increased." (PMID 36291148, 2022). "Taken together, we may safely conclude that STIM1 haploinsufficiency decreases TRPCs expression, and that the expression of TRPCs does not reach the necessary level for cardiac hypertrophy during pressure overload." (PMID 29145451, 2017). "Pyridostigmine attenuated cardiac hypertrophy and improved cardiac function, which was related to improved cholinergic transmission efficiency (decreased acetylcholinesterase and increased acetylcholine), inhibition of the CaN/NFAT3/GATA4 pathway and suppression of the interaction of Orai1/STIM1." (PMID 28296184, 2017). "Second, TAC-treated STIM1+/–mice failed to manifest evidence of cardiac hypertrophy." (PMID 29145451, 2017). "Indeed, mice lacking STIM1 showed less adverse structural remodeling in response to pressure overload-induced cardiac hypertrophy." (PMID 27150728, 2016). "Meanwhile, as a feedback, the alterations of phosphorylated AMPK could regulate STIM1-mediated SOCE by influencing STIM1 phosphorylation (Figure 4➄), but the effects seem not strong enough to reverse markedly increased/reduced STIM1 in cardiac hypertrophy/diabetic cardiomyopathy." (PMID 37685995, 2023).
colorectal cancer (21 papers, 2014 to 2025). A primary or metastatic malignant neoplasm that affects the colon or rectum. "STIM1 overexpression has been observed in a portion of colorectal cancer (CRC) patients and associated with cancer cell invasion and migration." (PMID 26543234, 2015). "STIM1 is a direct target of miR-185 in colorectal cancer cells, in which miR-185 inversely correlates with the expression of STIM1 and associated with the progression of colorectal cancer." (PMID 31252656, 2019). "The ectopic expression of STIM1 is critical for the acquisition of mesenchymal features in colorectal cancer cells." (PMID 36677874, 2023). "One study demonstrated that microRNA-185 regulates STIM1 repression through posttranscriptional mechanism in colorectal cancer (CRC)." (PMID 37542345, 2023). "Ectopic expression of COX2 and PGE2 sufficiently rescued the effect of STIM1 knock-down, indicating that colorectal cancer cell migration mediated by STIM1 originates from its regulation of COX-2 expression and subsequent PGE2 synthesis." (PMID 36612099, 2022). "Meanwhile, there is clear evidence that STIM1 proteins occur in a variety of cancer types, such a breast, cervical, glioblastoma, and colorectal cancers." (PMID 33333945, 2020). "Increased levels of STIM1 promotes growth and migration in colorectal cancer cells (CRC) and STIM1 elevated expression in CRC patients is associated with tumor size, invasion and metastasis." (PMID 32733237, 2020). "Colorectal cancer patients with a positive expression of STIM1 or/and with a high Orai1 expression had poorer prognoses and shorter overall survival rates." (PMID 30935064, 2019). "Specifically, loss of hsa-miR-10a that targets KLF4, as seen in STIM1 overexpression patients, led to upregulation of LPO and initiation of colorectal carcinomas." (PMID 26543234, 2015). "STIM1 overexpression promotes colorectal cancer progression, cell motility, and COX-2 expression." (PMID 39128711, 2024). "The high expression level of STIM1 correlates with an unfavorable prognosis in colorectal cancer." (PMID 36677874, 2023). "Interestingly, STIM1 was determined to be a direct target of miR-185, a microRNA (miRNA), in colorectal cancer tissues and cell lines." (PMID 36612099, 2022). "In prostate and lung cancers (LCs), resveratrol incites a downregulation of stromal interaction molecule 1 (STIM1) and an inactivation of the mTOR pathway whereas in colorectal cancer, it boosts autophagy by increasing reactive oxygen species (ROS) production and inducing caspases-8 and−3." (PMID 34540888, 2021). "Indeed, a correlation of increased expression of STIM1 and enhanced tumor size, tumor invasion and metastasis has been shown for colorectal cancer." (PMID 33333945, 2020). "Similarly, high levels of STIM1 were positively correlated to tumor invasion and metastasis in colorectal cancer, where endogenous levels were found to be upregulated in diseased tissue." (PMID 27417567, 2016). "Upregulated expression of STIM1 in colorectal cancer cells induced EMT, whereas STIM1 knock-down showed the opposite effect." (PMID 36612099, 2022). "STIM1 was found to drive migration by promotion of COX-2 expression and subsequent production of prostaglandin E2 in colorectal cancer cells." (PMID 27417567, 2016). "For example, in colorectal cancer cells, epidermal growth factor (EGF) increased expression of cyclooxygenase-2 via STIM1 and Orai1." (PMID 24586666, 2014). "In colorectal cancer cells the high STIM2 expression levels has been related with a reduced invasive phenotype, suggesting a cancer cell growth suppressor function in contrast to STIM1." (PMID 32733237, 2020). "Stromal interaction molecule 1 (STIM1), an endoplasmic reticulum Ca2+ sensor, is regulated by a post-transcriptional regulatory mechanism mediated by a novel EMT-inhibiting miRNA named miR-185 in the metastasis cascade of colorectal cancer." (PMID 27992370, 2017).
colorectal cancer (continued). "Targeting of STIM1 by knockdown or pharmacological inhibition of the store-operated calcium entry (SOCE) was shown to suppress tumor metastasis in melanoma, hepatocellular carcinoma, colorectal cancer and breast cancer and sensitized cancer cells’ response to therapy." (PMID 30544747, 2018). "However, our observations agree with others reporting that ASA administration impairs STIM1/Orai1 interaction, and hence, ASA reduces SOCE in colorectal cancer cells; meanwhile, other nonsteroidal anti-inflammatory drugs, such as sulindac, impair SOCE and STIM1 membrane translocation." (PMID 41155293, 2025).